SNORA1 (small nucleolar RNA, H/ACA box 1)
Synonyms: ACA1
Gene: Small nucleolar RNA gene on chromosome 11 (93,732,004 to 93,732,133, reverse strand). Ensembl gene ENSG00000206834.
Gene Ontology:
Biological process: RNA processing
Cellular component: nucleolus
Homologues: Orthologues: chimpanzee SNORA1 (100% identical), mouse Gm22620 (85% identical), rat Snora1b (78% identical). Paralogues in human: SNORA1B (97% identical).
Diseases named in the same sentence as SNORA1 in open-access papers:
SNORA1 is named in the same sentence as 2 diseases in open-access papers, as found by Europe PMC text mining. Sharing a sentence is not in itself a finding about the gene and the disease. The quoted sentences say what the papers report.
mastitis (1 paper, 2025). Inflammation of breast tissue during lactation or postpartum due to an obstructed duct or infection. "The genes correlated with downregulated SNORA1 (e.g., JAK2 and IL6R) have been shown to stimulate inflammation during subclinical mastitis as discussed in several reviews." (PMID 40936092, 2025).
SNORA1 also shares sentences with these, for which no sentence is quoted: infection (2 papers).